MMP9 (matrix metallopeptidase 9)
Diseases named in the same sentence as MMP9 in open-access papers (continued):
Sharing a sentence is not in itself a finding about the gene and the disease.
cancer (continued). "MMP9 and SCGN were generally associated with OS in pan-cancer, including ccRCC." (PMID 38375034, 2024). "MMP9 plays a crucial role in multiple stages of cancer development, including reducing cancer cell apoptotic potential, promoting angiogenesis, and modulating the immune response to cancer cells." (PMID 39336161, 2024). "The authors suggest that co-culture of A-MSCs and cancer cells may be a pro-tumorigenic factor promoting neoplastic invasion and increasing the level of MMP-9 and laminin." (PMID 39120301, 2024). "MMP-9 is another factor contributing to cancer cell migration and metastasis." (PMID 39125717, 2024). "Moreover, recent studies highlighted that the aberrant gene expression of NGAL and MMP-9 is strictly regulated by methDNA status in several pathological conditions, including cancer." (PMID 39358721, 2024). "Besides, it modifies the migration and invasion abilities of the cancer cells by regulating the MAPK-ERK/vascular endothelial growth factor (VEGF)/matrix metalloproteinase-9 (MMP-9) signaling pathway, and polyamine metabolism." (PMID 38915462, 2024). "ETS1 and MMP9 can regulate EMT and have both been frequently associated with cancer metastasis." (PMID 38732189, 2024). "As expected, ectopic MMP9 profoundly promoted cancer cell migration and invasion." (PMID 38355937, 2024). "The link between MMP9 and inflammation is evident from its correlation with inflammatory mediators like IL-6 and CRP, indicating an inflammatory environment that may boost MMP9 levels, thereby facilitating cancer’s advancement." (PMID 39664453, 2024). "High specificity for MMP-2 and MMP-9 reduces off-target effects and toxicity, providing a more targeted approach to cancer treatment, and these inhibitors also can be used in combination with other therapies, such as chemotherapy, radiation, and immunotherapy, to enhance treatment efficacy." (PMID 39858430, 2024). "In the context of inflammation and cancer progression, MMP9 is upregulated and may serve to disrupt cell-cell contact through E-cadherin." (PMID 39739829, 2024). "Moreover, two gelatinases (MMP-2 and MMP-9) have caught the spotlight due to their implication in several mechanisms such as angiogenesis and infiltration of cancer cells as well as metastasization." (PMID 38254117, 2024). "Moreover, given MMP9’s pivotal involvement in a spectrum of maladies including inflammation and cancer, isoquercitrin emerges as a promising therapeutic agent for these conditions." (PMID 39062794, 2024). "MMP-9, also known as gelatinase B, is a metal-dependent endopeptidase that is involved in angiogenesis, immune cell migration, chemokine and cytokine activation, and the progression of cancer cells." (PMID 38886354, 2024). "Therefore, further studies need to be done to clarify that our observation on TMZ-mediated promotion of MMP9 expression is mediated through cellular senescence induced by anti-cancer agent." (PMID 38906916, 2024). "Additionally, a significant increase in metalloproteinase MMP2 and MMP9 expression, which are linked to enhanced metastatic potential, further underscored the potential of LMF to influence PC3 cancer cell behaviour." (PMID 39336161, 2024). "Moreover, the expression of MMP-9 was downregulated, which significantly reduced the migration and invasion ability of cancer cells." (PMID 38248344, 2024). "The MMP9-driven macrophage activity not only supports cancer progression but also sets a precedent for systemic inflammatory responses that could amplify the susceptibility to neuropathic conditions." (PMID 39664453, 2024). "Lastly, chemotherapy itself, while aiming to eradicate cancer cells, may trigger MMP9 expression, linking cancer treatment directly to the aggravation of neuropathic conditions." (PMID 39664453, 2024). "Moreover, LCN2 is also known to associate with MMP9, preventing the degradation of the metalloproteinase that is involved in degrading ECM, enhancing cancer metastasis." (PMID 38612413, 2024).
cancer (continued). "Inhibiting MMP9 activity can help to impede cancer progression." (PMID 38291541, 2024). "have been documented to increase secretion of host MMPs, including MMP7, MMP13, MMP9, activated MMP9, involved in degradation of extracellular matrix, contributing both to increased invasion of the bacteria into the tissue and to cancer invasion." (PMID 38535967, 2024). "This study also sheds light on the downregulation of factors related to metastasis and angiogenesis, such as Cyclin D1, VEGF, and MMP-9, under combined treatment, emphasizing the potential therapeutic promise of this strategy for controlling cancer cell proliferation and metastasis." (PMID 38790669, 2024). "Reports also demonstrated that ECM1 could activate or inhibit the activity of MMP9 in different cancers and genodermatosis." (PMID 38546916, 2024). "In addition, both compounds decrease the MMP-2 and MMP-9 expression, which are important biomarkers of cancer progression and MAPK signaling." (PMID 39272835, 2024). "Among multiple MMPs, MMP-2 and MMP-9 have been reported to be involved in pathology of cancers." (PMID 38672151, 2024). "MMP9 can induce metastasis, and its increased expression facilitates cancer metastasis." (PMID 38419894, 2024). "MMP-2 and MMP-9 are highly expressed in various cancer cells and targeting MMPs with their inhibitors may act as an important therapeutics in cancers." (PMID 39062100, 2024). "Therefore, the interplay between the RAS/ERK pathway and N-cadherin, vimentin, and E-cadherin, as well as MMP-2 and MMP-9, is crucial for cancer cell proliferation and migration." (PMID 39769029, 2024). "Additionally, transfer of CD44 from the cancer cell-derived exosomes to HPMC induced the secretion of matrix metalloproteinase-9 (MMP-9) that dispersed the mesothelial barrier and promoted cancer invasion." (PMID 38796525, 2024). "Given the reported predictive role of MMP-2 and/or MMP-9 overexpression in metastatic progression in various cancers, we sought to investigate whether MMP-2 and/or MMP-9 genotypes were linked to metastatic risk in UTUC." (PMID 39063556, 2024). "MMP-2 and MMP-9 are part of the matrix metalloproteinase (MMP) family, known for their ability to break down polymeric collagen and the extracellular matrix (ECM), factors linked to cancer metastasis and angiogenesis." (PMID 38374934, 2024). "Pre-clinical studies employing both in vitro and animal models suggest that they mostly act by inhibiting MMP-2 and MMP-9 or their related pathways, indicating that polyphenolic compounds have considerable potential against the development and progression of cancers." (PMID 39335164, 2024). "This dual role of MMP9 in promoting inflammation suggests a vicious cycle where its elevated activity could worsen cancer outcomes and increase the vulnerability of patients to CIPN." (PMID 39664453, 2024). "Moreover, the inhibition of NF-κB signaling has been linked to decreased levels of anti-apoptotic protein, Bcl-2, and matrix metalloproteinase-9 (MMP-9), which plays a role in cancer metastasis." (PMID 39834817, 2024). "Moreover, both the repression of Mmp9 and the activation of Prrg2 were easily recapitulated in Zbtb11 KO MEFs, further confirming our previous results in cancer cells where MMP9 and PRRG2 are critical downstream targets of ZBTB11." (PMID 38355937, 2024). "Overall, these findings suggest that protein fractions in soybeans may play a more significant role in cancer prevention related to soy as MMP-9 inhibitors than previously thought." (PMID 39858430, 2024). "Matrix metalloproteinase-9 (MMP-9) is a Matrix metalloproteinase that helps degrade parts of the extracellular matrix and has also been found to be involved in processes such as inflammation, cancer invasion and metastasis." (PMID 38582791, 2024). "MMP9 and SCGN were poorly associated with microsatellite instability (MSI) in pan-cancer." (PMID 38375034, 2024).
cancer (continued). "Further future research could be crucial for understanding the broader implication of cancer treatment, especially the role of chemotherapy in influencing MMP9 activity and, consequently, neuropathic pain outcomes." (PMID 39664453, 2024). "HIF1α, MMP9 and β catenin are well known as cancer malignancy markers." (PMID 39273283, 2024). "The matriptase-activated PAR-2/PI3K/Akt/MMP9 signaling axis results in the cleavage of E-cadherin and the release of soluble E-cadherin, disrupting cell–cell interactions and facilitating peritoneal dissemination in cancer cells." (PMID 39408927, 2024). "Two metalloproteinases, ADAM metallopeptidase domain 19 (ADAM19) and matrix metallopeptidase 9 (MMP9), upregulated under hypoxia, are also associated with cancer progression, mainly through modulation of cell adhesion and migration in several cancers, including NSCLC." (PMID 38674080, 2024). "In pan-cancer, both MMP9 and SCGN were associated with multiple immune checkpoint molecules." (PMID 38375034, 2024). "One important concept is the significance of ETS1 in MMP9 expression and cancer metastasis." (PMID 38732189, 2024). "Similarly, findings from a recent study demonstrated that intragenic hypermethylation of MMP9 is linked to the overexpression of MMP-9, thereby contributing to the development and progression of cancer." (PMID 38473261, 2024). "The findings suggest that MMP-2 and MMP-9 may play crucial roles in the development of cancer, with MMP-2 serving as a potential biological marker for invasion and lymph node metastasis in OSCC." (PMID 38673838, 2024). "We found that prioritized ligands with a high impact on cancer gene expression, including Fn1, Mmp9, and Cd274, were mainly expressed in myeloid cells, suggesting that the molecular changes of cancer cells may be induced by myeloid cells." (PMID 38169569, 2024). "Furthermore, qPCR results showed a marked increase in MMP9 transcription was observed from HOXC10 overexpression cancer cells conditioned medium induced osteoclasts, which were partially abrogated by ERK1/2 inhibition." (PMID 39191757, 2024). "Therefore, targeting MMPs, specifically MMP-2 and MMP-9, represents a promising new therapeutics avenue for inhibiting cancer metastasis." (PMID 39431222, 2024). "In fact, the inhibition of NLRP3 expression reduced the migratory and invasive capacities of cancer cells, whilst also inverting the mesenchymal condition by reducing vimentin and Matrix metalloproteinase-9 (MMP9) expression and increasing E-cadherin expression." (PMID 39684769, 2024). "The presence of MMP9 in these stromal and cancer cells may promote tissue restructuring, angiogenesis, and cancer cell migration." (PMID 39234567, 2024). "Moreover, PTEN has been reported to inhibit cell invasion and migration by downregulation of the expression and enzymatic activity of MMP2 and MMP9 in multiple human cancers, including GC 27-30." (PMID 36778127, 2023). "MMP-9 overexpression is a common occurrence in the majority of cancer types." (PMID 38260844, 2023). "Therefore, highly selective and specific MMP-9 inhibitors should be discovered and screened in natural compounds or designed by synthetic methods and applied to anti-cancer targeting therapy." (PMID 37175113, 2023). "In addition, activated CD8 T cells release exosomes expressing FasL that can modulate MMP-9 expression in cancer cells and consequently lung metastasis." (PMID 37207158, 2023). "Moreover, the observation connected with the results of all measurements performed for MMP-2 and MMP-9 in the tissues shows that MMP-9 is more involved in the growing and spreading of cancer cells in the bladder than MMP-2." (PMID 36979935, 2023). "In addition to degrading various ECM components, MMP3 can activate MMP9 and the collagenases, and degrade a number of cell surface molecules, including E-cadherin which contributes to cancer development." (PMID 36677584, 2023).
cancer (continued). "In addition, the TPA-induced activity and expression of matrix metalloproteinase-9 (MMP-9), a crucial mediator of cancer dissemination, were found to be reduced in EF-24-treated cells." (PMID 36900342, 2023). "Additionally, the Western blot analysis revealed that the knockdown of SNHG3 significantly reduced the protein levels of proteins involved in the cell cycle (CDK6, CDK4, and Cyclin D1) as well as cancer metastasis (N-Cadherin, Vimentin, and MMP9)." (PMID 37348024, 2023). "In addition, in this study, we also observed that the expression of MMP9 was significantly correlated with cancer stem cells." (PMID 37200633, 2023). "Although iron chelators and anti-MMP9 moieties have continued to be studied separately, there is a need to further evaluate anti-Lcn-2 antibodies in clinical trials, and in combination with current therapies for specific cancer subtypes." (PMID 37958332, 2023). "However, some current findings have begun to highlight the role TANs play in MMP9 secretion to promote cancer progression and metastasis." (PMID 36836690, 2023). "MMP9 is also contained in NETs, whose release takes place in many types of cancer." (PMID 37444436, 2023). "Targeting to MMP-9, one study has achieved highly sensitive imaging of cancer." (PMID 36978072, 2023). "Therefore, control of the levels and actions of MMPs, especially MMP-2 and MMP-9, is necessary to care for and/or cure cancer and AD." (PMID 36674771, 2023). "Moreover, GM-CSF, TNF-α, MMP-2, MMP-9, and proinflammatory cytokines such as IL-1β and IL-6 are involved in NF-κB and AP-1-mediated cancer progression." (PMID 37298797, 2023). "And PGE2 was reported to promote cancer migration via inducing MMP-9 expression." (PMID 38136676, 2023). "Additionally, recent work identified MMP-9 expression by cancer cells arrested on brain capillaries as a key mediator of capillary remodeling during brain metastasis." (PMID 37924145, 2023). "Additionally, we examined the expressions of IL-8, CXCR1, and CXCR2, which we previously reported, and MMP9 expression of cancer nests in the human ESCC tissues." (PMID 37296952, 2023). "We hypothesize that cancer cells and M2-like macrophages closely communicate at the invasive front, resulting in MMP9 expression." (PMID 37296952, 2023). "Laminin stimulates the expression of MMP-9 and its involvement in different cancers." (PMID 36982551, 2023). "An increase in IL-8 associated with BRAF mutation has been demonstrated to be essential for the induction of MMP-2 and MMP-9 that contribute to cell migration and to angiogenesis enhancing cancer vascularization to support the oxygen retrieval and nutrient supply to cancer cells." (PMID 37627054, 2023). "Importantly, studies reported that stimulation of cancer cells with PMA induces MMP-9 expression via activation of NF-κB signaling pathway." (PMID 37372062, 2023). "ERK activation in LC resulted to MMP-9 expression, thus led to cancer migration and development." (PMID 37766868, 2023). "Overall, all the available evidence indicates that since MMP-9 has a significant role in tumorigenesis and metastasis, one of the possible ways of controlling cancer and metastasis would be to either to inhibit the enzyme directly or inhibit the pathways that lead to the upregulation of the gene." (PMID 37077369, 2023). "CXCR2 expression was significantly associated with cancer nest MMP9 expression (p = 0.010) whereas CXCR1 was not (p = 0.591)." (PMID 37296952, 2023). "Among MMPs, MMP-2 and MMP-9 have been reported to be involved in cancer progression and metastasis." (PMID 36674771, 2023). "According to previous research, MMP-9 is overexpressed in cancer cells." (PMID 36837487, 2023). "Moreover, a correlation was also observed between the higher MMP-9 activity and the increase in the potential for metastasis of cancer cells." (PMID 37509417, 2023).
cancer (continued). "We selected MMP9 for further validation as it was reported as an oncogene in multiple cancer types, including HCC, and BA treatment could promote MMP9 expression." (PMID 37234174, 2023). "MMP-9 may downregulate the IL receptor found on the surface of T lymphocytes, and may suppress immunity and promote cancer development." (PMID 37895400, 2023). "Additionally, the expression of MMP-9 and the activation of the integrin-β1/FAK pathway have been associated with cancer cell invasion, metastasis, and cell motility." (PMID 38260844, 2023). "MMP9, a member of the matrix metalloproteinase family (MMPs), is located on human chromosome 20 and is one of the most important enzymes in the breakdown of the extracellular matrix, playing a key role in the invasion and metastasis of cancer." (PMID 36726839, 2023). "Importantly, high levels of serum MMPs are also reliable biomarkers indicative of metastatic progression and are associated with poor survival in gastric (MMP-14) and breast (MMP-2 and MMP-9) cancer patients." (PMID 37350937, 2023). "MMP-9 affects remodeling of the extracellular matrix and cancer invasiveness." (PMID 36978072, 2023). "NE and MMP9 cleave laminin to induce the proliferation of dormant cancer cells." (PMID 37936694, 2023). "Previous reports indicate that the removal of MMP9 expression increases the secretion of IL-4 and IL-13 in the inflammation of respiratory airways, suggesting the existence of a self-regulatory loop between IL-13 and MMP9 expression to sustain cancer-enabling inflammation." (PMID 37963919, 2023). "Taken together, one can see that the mast cell-derived chymase may promote not only cancer development but also cancer metastasis through the activation of TGFβ1, MMP-9, and VEGF." (PMID 37175975, 2023). "In the network, eight genes related to the apoptotic process and cell migration, including Mmp9, Cxcl12, Cdh1, Fap, Itga6, Mdk, Aif1, and Mif, were downregulated with co-treatment, which may play vital roles in inhibition of cancer progression and cell death." (PMID 36765032, 2023). "MCSs display an increase in both CD44 (cancer stemness) and MMP9 (metastasis) expression." (PMID 37048115, 2023). "Additionally, it has been shown that MMP-3 can activate other metalloproteinases, such as MMP-1, MMP-7, and MMP-9, mainly to activate cancer cell division." (PMID 38203373, 2023). "MMP-9 also plays a significant role in the progression of cancer cells." (PMID 38203373, 2023). "Additionally, the connection of Wnt signaling and MMP-9 expression has been extensively studied in various cancers." (PMID 38068928, 2023). "In addition, KT suppressed the expression of HIF1α, MMP-2, and MMP-9, which also play a significant role in bone metabolism and metastasis of cancer." (PMID 36674719, 2023). "Additionally, TANs produce MMP-9 and neutrophil elastase to promote the extravasation of cancer cells and drive disseminated cancer cells to metastasise." (PMID 37480104, 2023). "In addition, NE and MMP-9 can cleat membrane protein to induce the proliferation of dormant cancer cells in metastatic sites." (PMID 37152022, 2023). "Activation of STAT3 could significantly increase the expression of the metastasis-related proteins MMP-2 and MMP-9 in cancer cells." (PMID 37049904, 2023). "The activation of MAPKs and NF-κB could upregulate the levels of MMP-2 and MMP-9 in cancer cells and other pathological conditions." (PMID 38069361, 2023). "The MMP-9 function may depend on the cancer disease state, such as the presence of fibronectin, which in turn elevates the level of proteases." (PMID 36910158, 2023). "Notably, the postoperative rise in MMP-9 was consistent among all cancer types, although to varying degrees and returned to baseline 24 h after surgery." (PMID 38067195, 2023). "Notably, the identification of some Mmps (Mmp1, Mmp2, Mmp7 and Mmp9) has been reported as Myb-regulated genes in cancer cells." (PMID 37701782, 2023).